PTPN6 (protein tyrosine phosphatase non-receptor type 6)
Diseases named in the same sentence as PTPN6 in open-access papers (continued):
Sharing a sentence is not in itself a finding about the gene and the disease.
kidney disease (2 papers, 2017 to 2022). "Both PTPN6 and PHB223–26 have been implicated in experimental models of kidney disease." (PMID 29097680, 2017). "Some studies indicated that enhanced renal expression of PTPN6 (encoding Protein Tyrosine Phosphatase Non-Receptor Type 6, known also as Src homology-2 domain-containing phosphatase-1 (SHP-1)) was associated with renal disease and vascular complications in diabetes." (PMID 35806113, 2022).
neurodegenerative disease (2 papers, 2023 to 2025). A disorder of the central nervous system characterized by gradual and progressive loss of neural tissue and neurologic function. "Since PTPN6 was reported to be critical in inhibiting MG Aβ phagocytosis, PTPN6 DNA hypomethylation and increased expression in AD MG may contribute to Aβ plaque accumulation and other neurodegenerative diseases." (PMID 37789414, 2023).
inflammation (1 paper, 2017). Aberrant reaction of the microcirculation characterized by movement of fluid and leukocytes from the blood into extravascular tissues. "Overexpression of PTPN6 for the duration of Al2O3 NPs-exposure protected mice from airway inflammation (by reducing the numbers of total cell, neutrophil and macrophages; as well as the inflammatory mediator levels in BALF)." (PMID 29233151, 2017).
metabolic disease (1 paper, 2022). A congenital disorder (due to inherited enzyme abnormality) or acquired (due to failure of a metabolically important organ) disorder resulting from an abnormal metabolic process. "Among PTPs, protein tyrosine phosphatase non-receptor type 6 (PTPN6) has also been a target of major interest for metabolic diseases." (PMID 35563411, 2022).
PTPN6 also shares sentences with these, for which no sentence is quoted: lymphoma (3 papers); acute lymphoblastic leukaemia (2); Hyperinsulinemia (2); leishmaniasis (2); liver cancer (2); renal cell carcinoma (2); uterine carcinosarcoma (2); allergic asthma (1); anaplastic glioma (1); anaplastic large cell lymphoma (1); anaplastic oligodendroglioma (1); auto‐inflammatory syndromes (1); brain tumours (1); celiac disease (1); cerebrovascular disease (1); cognitive decline (1); coinfection (1); E. coli infection (1); endotoxemia (1); familial Mediterranean fever (1); follicular lymphoma (1); helminth infections (1); hematopoietic cancers (1); hyperprolactinemia (1); Hypoalbuminemia (1); Immunodeficiency (1); inflammatory bowel disease (1); influenza (1); insomnia (1); lung squamous cell cancer (1).
A further 25 diseases each share a sentence with PTPN6 in 1 paper.